PPP1R14B (protein phosphatase 1 regulatory inhibitor subunit 14B)
Diseases named in the same sentence as PPP1R14B in open-access papers:
PPP1R14B is named in the same sentence as 34 diseases in open-access papers, as found by Europe PMC text mining. Sharing a sentence is not in itself a finding about the gene and the disease. The quoted sentences say what the papers report.
prostate carcinoma (5 papers, 2018 to 2025). A carcinoma that arises from epithelial cells of the prostate gland. "The frequent amplification of the PPP1R14B gene is associated with poor survival outcomes, as observed in bladder, endometrial, and prostate cancers." (PMID 40149880, 2025). "Prostate cancer and breast cancer cases with altered PPP1R14B showed poorer clinical survival compared with the unaltered PPP1R14B group." (PMID 34858479, 2021). "The prostate cancer cases with altered PPP1R14B also showed poor OS (p = 2.59e-14)." (PMID 34858479, 2021). "A bioinformatics analysis showed that PPP1R14B was significantly overexpressed in plasma mRNAs in PCa (prostate cancer) patients, but the role of PPP1R14B in cancer was still unknown." (PMID 34858479, 2021). "PPP1R14B was significantly overexpressed in OCCC and associated endometriosis and overexpressed in plasma messenger RNAs in PCa (prostate cancer) patients, but the role of PPP1R14B in cancer was still unknown." (PMID 34858479, 2021). "Furthermore, we also observe significant overexpression of PPP1R14B in human prostate cancer following interrogation of publicly available datasets." (PMID 29423094, 2018).
uterine corpus endometrial carcinoma (4 papers, 2021 to 2024). A endometrial carcinoma (disease) that involves the body of uterus. "Association between the expression of PPP1R14B and clinical features of samples with uterine corpus endometrial carcinoma." (PMID 36824011, 2023). "Although PPP1R14B may have a certain correlation with the prognosis of uterine corpus endometrial carcinoma, breast cancer and gastrointestinal cancer 69-71, its relationship with PCa has not been studied yet." (PMID 39668827, 2024). "The results showed that the PPP1R14B protein was highly expressed in ccRCC (Clear cell renal cell carcinoma), COAD, LUAD, OV, and UCEC (Uterine corpus endometrial carcinoma) compared with the normal tissues." (PMID 34858479, 2021). "Although it has been reported that PPP1R14B may have a certain correlation with the prognosis of uterine corpus endometrial carcinoma, breast cancer and gastrointestinal cancer, there are none of studies about correlation between PPP1R14B and PCa." (PMID 39668827, 2024).
breast carcinoma (3 papers, 2019 to 2024). "PPP1R14B interacts with ROCK2 (“IntAct” EBI-7009696), which is a key regulator of the actin cytoskeleton and cell polarity and is one of the most highly overexpressed phosphatase-related proteins in triple-negative breast cancer (TNBC), which has the worst prognosis among all breast cancers." (PMID 31652503, 2019).
chronic lymphocytic leukemia (2 papers, 2021 to 2023). "The recent studies showed that SCGB2A1, KLF4, and PPP1R14B can differentiate a group of circa 5% of cases with less survival in chronic lymphocytic leukemia (CLL) patients, which might be useful for further research about disease prognostication and drug response in CLL." (PMID 34858479, 2021).
endometriosis (2 papers, 2018 to 2021). The growth of functional endometrial tissue in anatomic sites outside the uterine body. "PPP1R14B was significantly overexpressed in ovarian clear cell carcinoma (OCCC) and associated endometriosis." (PMID 34858479, 2021). "It was reported that OCCC-associated endometriosis already harbors aberrant gene expression, such as altered expressions of eEF1A2, PTCH2, PPP1R14B, and XRCC5, which may not be found in endometriosis tissue in the absence of cancer." (PMID 29941051, 2018).
liver cancer (2 papers, 2022 to 2025). An epithelial or non-epithelial malignant neoplasm that arises from the liver. "The results showed that only four genes, including ATP6V1F, PPP1R14B, BTF3L4 and SLC7A5, were oncogenes that are required for cell proliferation of stomach cancer, liver cancer and colorectal cancer." (PMID 36620589, 2022). "The gene expression correlation analysis showed that miR-194 expression showed a negative correlation with the expression of ATP6V1F, PPP1R14B, BTF3L4 and SLC7A5 in gastric cancer, liver cancer and colorectal cancer." (PMID 36620589, 2022).
ovarian clear cell cancer (2 papers, 2018 to 2023). An invasive malignant neoplasm that arises from the ovary and is characterized by a predominance of clear and hobnail malignant epithelial cells. "Similarly, PPP1R14B has been reported to be overexpressed in ovarian clear cell carcinoma, as well as serving as an unfavourable prognostic marker in liver and pancreatic cancers." (PMID 29423094, 2018).
pancreatic cancer (2 papers, 2018 to 2022). "Out of 11 ITGA3, MET, FNDC3B, PPP1R14B and KIAA0513, including PLAU, were previously reported as individual prognostic markers in the pancreatic cancer TCGA-PAAD cohort." (PMID 36591282, 2022).
acute myeloid leukaemia (1 paper, 2023). "In adrenocortical carcinoma (ACC, T = 77, N = 128), acute myeloid leukaemia (LAML, T = 173, N = 70), and skin cutaneous melanoma (SKCM, T = 469, N = 813), the expression of PPP1R14B was lower than that in normal tissues, and the differences were statistically significant (p < 0.05)." (PMID 36824011, 2023).
cleft palate (1 paper, 2025). Cleft palate is a fissure type embryopathy that affects the soft and hard palate to varying degrees. "In addition, Ppp1r14b may have an important gene interaction with these pathways during atRA exposure, inducing cleft palate." (PMID 41301924, 2025).
colorectal cancer (1 paper, 2022). A primary or metastatic malignant neoplasm that affects the colon or rectum. "Consistent with our results, ATP6V1F, PPP1R14B and SLC7A5 were reported to play oncogenic roles in colorectal cancer progression." (PMID 36620589, 2022).
endometrial cancer (1 paper, 2023). Primary or metastatic malignant neoplasm involving the endometrium (mucous membrane that lines the endometrial cavity). "Given that endometrial cancer formation is associated with dysplasia caused by oestrogen overstimulation, this result suggests that involvement in this process may also be one of the mechanisms by which PPP1R14B promotes endometrial cancer development." (PMID 36824011, 2023). "Therefore, we hypothesized that PPP1R14B may play a role in promoting endometrial cancer by promoting the function of keratin‐related proteins and keratin." (PMID 36824011, 2023). "In addition, among the genes closely associated with PPP1R14B expression, UBE2S, JPT1, and PTTG1 were associated with abnormal expression of endometrial cancer desiccations, proliferation, migration, methylation, and prediction of response to metformin therapy." (PMID 36824011, 2023).
glioma (1 paper, 2022). A benign or malignant brain and spinal cord tumor that arises from glial cells (astrocytes, oligodendrocytes, ependymal cells). "A study shows that PPP1R14B is highly expressed in glioma and leads to bad outcome for patients." (PMID 36606241, 2022).
cancer (12 papers, 2011 to 2025). A tumor composed of atypical neoplastic, often pleomorphic cells that invade other tissues. "In this study, we identified 21 miRNAs associated with PPP1R14B, which play important roles in various cancers." (PMID 39668827, 2024). "In order to more systematically clarify the mutation feature and biological functions of PPP1R14B in tumor progression, we used the cBioPortal web to investigate the genetic alteration status of PPP1R14B in human pan-cancer." (PMID 34858479, 2021). "Additionally, we explored the association between genetic alteration of PPP1R14B and clinical survival in different cancer." (PMID 34858479, 2021). "Mutation feature analysis of PPP1R14B in pan-cancer suggested that the highest alteration frequency of PPP1R14B (>4%) appears for patients with bladder/urinary tract cancer with “Amplification” as the primary type, and the genetic alteration of PPP1R14B in tumors changed its mRNA expression." (PMID 34858479, 2021). "In summary, PPP1R14B can affect the prognosis of pan-cancer and is closely related to immune infiltration." (PMID 34858479, 2021). "Herein, we found that PPP1R14B was involved in the prognosis of pan-cancer and closely related to immune infiltration." (PMID 34858479, 2021). "Here, we found that the PPP1R14B expression level was positively correlated with MDSC infiltration in many cancer types." (PMID 34858479, 2021). "The expression of NUBP2, PLCB3, PPP1CA, TBCB, and UBE2C were positively correlated with PPP1R14B in the majority of cancer types." (PMID 34858479, 2021). "Then, we retrieved the PPP1R14B expression data from TCGA pan-cancer dataset and found that PPP1R14B was amplified along with the significantly high mRNA expression." (PMID 34858479, 2021). "Next, we investigated the expression of PPP1R14B according to the pathologic stage of the patients in the TCGA cancer type." (PMID 34858479, 2021). "The results showed that in most cancer types, the expression of PPP1R14B is positively correlated with the MDSC infiltration level." (PMID 34858479, 2021). "Pan-cancer analysis revealed that increased PPP1R14B expression correlated with poor prognosis and increased immune infiltration levels in myeloid-derived suppressor cells (MDSCs), and PPP1R14B could be used as a prognostic biomarker for pan-cancer." (PMID 36591282, 2022). "PPP1R14B can be used as a prognostic biomarker for pan-cancer." (PMID 34858479, 2021). "In addition, this study only conducted a bioinformatics analysis concerning the role of PPP1R14B in pan-cancer across different databases, and in vivo and in vitro experiment verification and further mechanism research is also needed." (PMID 34858479, 2021). "Our data highlighted that the PPP1R14B network was one of the main protein networks related to cancer, and further study of its function in tumors may provide clues for new cancer treatment strategies." (PMID 34858479, 2021). "We divided cancer cases into high-expression and low-expression groups according to the mRNA expression level of PPP1R14B and investigated the correlation between PPP1R14B expression and the prognosis of patients with different tumors in the TCGA and GEO datasets." (PMID 34858479, 2021). "However, even though we integrated information across multiple databases about the role of PPP1R14B in pan-cancer, this study still had limitations." (PMID 34858479, 2021). "Our studies suggest that PPP1R14B can be used as a prognostic biomarker for pan-cancer." (PMID 34858479, 2021). "In our study, we found that PPP1R14B was highly expressed in most types of tumors, and there were significant differences in early stages, which indicate a possible involvement of PPP1R14B in the initiation of cancer." (PMID 34858479, 2021).
cancer (continued). "In addition, patients with a high level of PPP1R14B predicted poor clinical outcomes in pan-cancer." (PMID 34858479, 2021). "Mmu-miR-505-5p was downregulated in Sca-1+CD31− compared to Sca-1+CD31+ cells, with targets Cyp1b1, Dcbld2, Igf1, and Ppp1r14b,Txndc5 increased in expression; Igf1 was involved in mTOR and PI3K-Akt signaling and Cyp1b1by with microRNAs in cancer." (PMID 27298624, 2016). "This indicates a possible involvement of PPP1R14B in the initiation but not the progression of cancer." (PMID 34858479, 2021). "There is also no pan-cancer evidence for the relationship between PPP1R14B and various tumor types based on abundant clinical data." (PMID 34858479, 2021). "There was also lack of pan-cancer evidence for the relationship between PPP1R14B and various tumor types based on abundant clinical data." (PMID 34858479, 2021).
tumor (9 papers, 2021 to 2025). "In summary, PPP1R14B was a potential diagnostic and prognostic biomarker of PCa and its high expression had closely association with tumor immune inhibition, proliferation and migration, providing a new target for drug therapy and immunotherapy in PCa." (PMID 39668827, 2024). "Then, we found a significant difference in PPP1R14B expression between patients with endometrioid and serous histological types of tumours, suggesting that PPP1R14B is indeed associated with poor prognosis." (PMID 36824011, 2023). "The results revealed that PPP1R14B expression was indeed closely associated with tumour development." (PMID 36824011, 2023). "Our study suggested that the high expression of PPP1R14B may be related to gene mutation and tumour proliferation, invasion, and metastasis in UCEC patients." (PMID 36824011, 2023). "Furthermore, in order to reveal the mechanism of PPP1R14B in tumor progression, our study identified co-expression genes associated with the PPP1R14B protein network." (PMID 34858479, 2021). "Notably, multivariate analysis revealed that PLAU protein upregulation in association with ITGA3, and PPP1R14B expression, tumour stage, and smoking history could predict poor overall survival in PDAC." (PMID 36591282, 2022). "Next, we evaluated the expression of PPP1R14B in 10 UCEC tumour tissues and 10 adjacent tissues by Western blot analysis." (PMID 36824011, 2023). "The predictive ability of the variable PPP1R14B was somewhat accurate in predicting the prognostic outcome of tumour patients versus normal patients (AUC = 0.955, CI = 0.930–0.981)." (PMID 36824011, 2023). "A recent study also showed that PPP1R14B was highly expressed in tumour tissues, and its high expression predicted a shorter survival time for patients." (PMID 36824011, 2023). "The expression of PPP1R14B was significantly correlated with histological grade, histological type and tumour invasion." (PMID 36824011, 2023). "Multivariate Cox regression analysis demonstrated that three prognostic proteins (PLAU, ITGA3, and PPP1R14B expression) and two clinicopathological factors (tumour stage and tobacco smoking history) were significantly associated with poor survival." (PMID 36591282, 2022). "Then, we used the GEPIA2 tool to combine all tumor expression data of TCGA and obtained the top 100 genes related to the expression of PPP1R14B." (PMID 34858479, 2021). "Recent studies also showed that PPP1R14B were highly expressed in tumor tissues and patients with high expression of PPP1R14B had poor survival rates." (PMID 34858479, 2021). "Recent studies have shown that PPP1R14B was highly expressed in tumor tissues and patients with high expression of PPP1R14B had poor survival rates." (PMID 34858479, 2021). "Our study indicates that Ppp1r14b is highly expressed in the atRA-exposed group, a group that inhibits the proliferation of mesenchymal and epithelial cells, a finding that contradicts previous research on tumor biology." (PMID 41301924, 2025). "In addition, the enrichment results also showed that the pathways related to the overexpression of PPP1R14B were involved in the proliferation, apoptosis and migration of tumor cells." (PMID 39668827, 2024). "In addition, 105 UCEC clinical samples were collected to further verify the expression of PPP1R14B in tumours and adjacent tissues, and the results of bioinformatics analysis were verified by experiments." (PMID 36824011, 2023). "The expression levels of PPP1R14B also differed among patients with different levels of tumour invasion, suggesting that the level of tumour invasion may also be correlated with the expression of PPP1R14." (PMID 36824011, 2023). "This was consistent with the results of bioinformatics analysis, indicating that high expression of PPP1R14B may indicate poor prognosis of tumour patients." (PMID 36824011, 2023). "PPP1R14B expression was higher in UCEC tumour tissues than in normal tissues." (PMID 36824011, 2023).
tumor (continued). "The expression of PPP1R14B was higher in UCEC tumour tissues than in adjacent tissues." (PMID 36824011, 2023). "Our studies suggested that PPP1R14B is involved in the tumor immunology process." (PMID 34858479, 2021). "Therefore, we further analyzed the expression difference of the PPP1R14B protein between tumor and normal tissues using data from the Clinical Proteomic Tumor Analysis Consortium (CPTAC)." (PMID 34858479, 2021). "Because the microarray and sequencing data about PPP1R14B were collected by analyzing tumor tissue information, the immune cell marker analysis could have introduced systematic bias." (PMID 34858479, 2021). "Our findings may provide an antitumor strategy targeting PPP1R14B, including manipulation of tumor cell growth or the tumor microenvironment, especially myeloid-derived suppressor cell infiltration." (PMID 34858479, 2021). "However, how the elevated expression of PPP1R14B in tumor tissues induces an increase of the MDSC infiltration level should be further investigated." (PMID 34858479, 2021). "However, the function and mechanisms of PPP1R14B in tumor progression remain ill defined." (PMID 34858479, 2021). "Upregulation of Ppp1r14b inhibits PP1 expression, enhancing proliferation and invasion across various tumor cells." (PMID 41301924, 2025). "GSEA results showed that PPP1R14B was closely related to H3K27me3, PRC2, and other epigenetic genes, which are closely related to the stem cell characteristics of tumour cells." (PMID 36824011, 2023). "Our finding highlights that miR-194 exerts a tumor-suppressive role in digestive system cancers by targeting ATP6V1F, PPP1R14B, BTF3L4 and SLC7A5." (PMID 36620589, 2022). "Transcriptome sequencing and Genome-wide CRISPR/Cas9 proliferation screening confirmed that miR-194 play tumor suppressive roles in GIC mainly by targeting ATP6V1F, BTF3L4, PPP1R14B and SLC7A5." (PMID 36620589, 2022). "To determine the differences of PPP1R14B expression between tumor and adjacent normal tissues, we used the TIMER2.0 database to analyze PPP1R14B mRNA expression levels across all TCGA tumors." (PMID 34858479, 2021). "PPP1R14B expression in UCEC was higher than that in normal tissues, suggesting that PPP1R14B may be involved in the occurrence and development of tumours." (PMID 36824011, 2023). "Finally, the experimental validation confirmed that knockdown of three identified lncRNA (LINC00963, PPP1R14B.AS1, and ZNF667.AS1) suppressed the invasive ability of tumor cells in vitro." (PMID 35774794, 2022).
PPP1R14B also shares sentences with these, for which no sentence is quoted: glioblastoma (3 papers); infection (3); triple-negative breast carcinoma (3); cervical cancer (2); lung carcinoma (2); adrenocortical carcinoma (1); bacterial infection (1); Clear cell renal cell carcinoma (1); colorectal adenoma (1); diffuse large B-cell lymphoma (1); digestive system cancer (1); hepatocellular carcinoma (1); lung adenocarcinoma (1); melanoma (1); ovarian serous cystadenocarcinoma (1); Pan (1); skin cutaneous melanoma (1); stomach cancer (1); uterine carcinosarcoma (1).